CCND1 (cyclin D1)
Diseases named in the same sentence as CCND1 in open-access papers (continued):
Sharing a sentence is not in itself a finding about the gene and the disease.
mantle cell lymphoma (280 papers, 1997 to 2026). Mantle cell lymphoma is a rare form of malignant non-Hodgkin lymphoma affecting B lymphocytes in the lymph nodes in a region called the ``mantle zone''. "Cyclin D1 is a proto-oncogene that is generally expressed by mantle cell lymphoma, its variants, and many other neoplasms." (PMID 36312606, 2022). "In the cases with blastoid morphology, two main differential diagnoses need to be ruled out, namely B-lymphoblastic lymphoma/leukemia (positive for TdT and/or CD34) and the blastoid variant of mantle cell lymphoma (positive for Bcl-1/cyclin D1 and/or SOX11)." (PMID 33322508, 2020). "Mantle cell lymphoma (MCL) is an incurable B‐cell lymphoma characterized by a translocation that juxtaposes the CCND1 gene (which encodes cyclin D1, CD1) on chromosome 11q13 and an immunoglobulin heavy chain gene promoter on chromosome 14q32." (PMID 31517438, 2019). "One study notably investigated perinucleolar localization and the binding of NCL to the CCND1 allele, which encoded the transcription of the cyclin D1 protein in mantle cell lymphoma." (PMID 31127617, 2019). "Of interest in this regard, the mTOR inhibitor temsirolimus is approved in the European Union for the treatment of mantle cell lymphoma, a disease whose hallmark is CCND1/BCL-1 translocation, resulting in overexpression of CCND1." (PMID 25596748, 2015). "Gain of function mutations have been found in the CCND1 gene encoding Cyclin D1 in mantle cell lymphoma (MCL) tumors." (PMID 23658553, 2013). "Cyclin D1 was included to exclude the remote possibility of a blastoid variant of mantle cell lymphoma, and also because plasma cell myeloma can be cyclin D1-positive." (PMID 23285191, 2012). "Chromosomal rearrangement is another cause of Cyclin D1 over-expression associated with centrocytic lymphomas, parathyroid adenomas and mantle cell lymphoma." (PMID 21347341, 2011). "Aberrant expression of cyclin D1 is a common feature in multiple myeloma (MM) and always associated with mantle cell lymphoma (MCL)." (PMID 20459741, 2010). "Burkitt's lymphoma is usually associated with a translocation of c-myc and CCND1 has been suggested as a marker for mantle cell lymphoma." (PMID 12237776, 2002). "However, a few cases of HGBL showed expression of cyclin D1 and were not limited to only mantle cell lymphoma and its variants." (PMID 36312606, 2022). "Mantle cell lymphoma is a non-Hodgkin lymphoproliferative neoplasm with several clinical and morphologic variants linked, primarily, through genetic derangement of the cyclin D1 locus." (PMID 32257467, 2020). "Furthermore, the cell cycle regulator Cyclin D1 can serve as a proto-oncogene, and Cyclin D1 overexpression is the hallmark of malignant transformation in mantle cell lymphoma (MCL)." (PMID 23382905, 2013). "In mantle cell lymphoma (MCL), chromosomal rearrangements cause Cyclin D1 overexpression, enhancing mTORC1-dependent cell cycle progression." (PMID 41356921, 2025). "Further evidence for these processes have been demonstrated in mantle cell lymphoma (MCL), where immunoblotting has found that oncogenic mRNA encoding cell proliferation factors such as Cyclin D1, PIM-1, and c-Myc are indeed exported via XPO1." (PMID 36671496, 2023). "Cyclin D1 expression is known to be expressed by mantle cell lymphoma (MCL), particularly pleomorphic and blastoid variants." (PMID 36312606, 2022). "USP2 inhibition by ML364 induces an increase in cellular cyclin D1 degradation and causes cell cycle arrest in mantle cell lymphoma (MCL) cell line (Mino cell)." (PMID 34454635, 2021). "Cyclin D1 translocation, associated with mantle cell lymphomas (MCL), occurs either during AID-induced somatic hypermutation (SHM) or AID-induced class switch recombination (CSR)." (PMID 32793219, 2020). "SOX 11, a nuclear protein expression, is a useful marker to identify mantle cell lymphoma, beyond cyclin D1 positivity." (PMID 40506992, 2025).
mantle cell lymphoma (continued). "The typical lymphoma with lymphomatous polyposis is mantle cell lymphoma, described by overexpression of the anti-cyclin D1 antibody." (PMID 38698463, 2024). "Rarely, CLL cases exhibit an IGH::CCND1 rearrangement, presenting a diagnostic challenge in distinguishing between clonal evolution within CLL and an independent mantle cell lymphoma." (PMID 39691246, 2024). "Examples include acute myeloid leukemia (AML) with defining genetic alterations, BCR::ABL1-positive chronic myeloid leukemia (CML), or CCND1 rearrangements in mantle cell lymphoma (MCL)." (PMID 38769532, 2024). "Mantle cell lymphoma (MCL) is a mature B-cell lymphoma associated with cyclin D family rearrangements and typically expresses CD5 and cyclin D1." (PMID 38938449, 2024). "The routine clinical practice for IGH rearrangement uses FISH assays, which only evaluate the common diagnostically important IGH fusions such as IGH::CCND1 in mantle cell lymphoma." (PMID 37206267, 2023). "Blocking the nuclear export of CCND1 resulted in a significant decrease in migration and invasion, indicating that cytoplasmic CCND1 is essential for chemotaxis and the invasion of mantle cell lymphoma cells." (PMID 37510349, 2023). "Cyclin D1 IHC has been a key tool in distinguishing mantle cell lymphoma from other small B cell lymphomas but suffers from technical difficulties and ambiguous staining results." (PMID 37894399, 2023). "The demonstration of IGH::CCND1 rearrangement leading to cyclin D1 overexpression can occur in DLBCL and poses a diagnostic challenge with blastoid or pleomorphic mantle cell lymphoma." (PMID 37555980, 2023). "CCND1 can also affect the movement and invasiveness of mantle cell lymphoma cells by localising and accumulating in the cytoplasm." (PMID 37510349, 2023). "Since blastoid mantle cell lymphoma is relatively easier to diagnose based on expression of cyclin D1 or/and CCND1 rearrangement, we focused on the differential diagnosis of blastoid HGBL, either DHL or NOS, versus B-ALL." (PMID 36765805, 2023). "Mantle cell lymphoma (MCL) is a subtype of B cell non-Hodgkin lymphoma (NHL) characterized by overexpression of CCND1 and translocation t(11:14)(q13;q32)." (PMID 37626420, 2023). "Cell cycle dysregulation characterized by cyclin D1 overexpression is common in mantle cell lymphoma (MCL), while mitotic disorder was less studied." (PMID 36882855, 2023). "Mantle cell lymphoma (MCL) is an aggressive B-cell non-Hodgkin lymphoma (NHL) subtype characterized by overexpression of CCND1 and SOX11 genes." (PMID 36359790, 2022). "Cyclin D1, which has a role in stimulating the G1/S transition of the cell cycle, is typically overexpressed in mantle cell lymphoma and has been regarded as a crucial oncogene in this disease." (PMID 36312606, 2022). "The negativity for CD10, CD23, cyclin D1, and BCL6 can be helpful in the differential diagnosis of OAMZL versus small lymphocytic lymphoma (CD23+), mantle-cell lymphoma (cyclin D1+), and follicular lymphoma (CD10+BCL6+)." (PMID 35267569, 2022). "Overexpression of cyclin D1 protein is found in many human tumors such as mantle cell lymphoma, non-small cell lung cancer, plasma cell myeloma, hairy cell leukemia, as well as breast and esophageal cancers." (PMID 36136690, 2022). "Mantle cell lymphoma (MCL) is a B-cell non-Hodgkin’s Lymphoma with characteristic deregulation of cell cycle arrest most commonly occurring due to gene translocation of Cyclin D1." (PMID 33799484, 2021). "Overexpression of cyclin D1 and consequent activation of CDK4/6 is a hallmark of mantle cell lymphoma (MCL); the CDK4 inhibitor palbociclib has shown modest clinical activity but was found to sensitize MCL cells to PI3K inhibitors." (PMID 33401428, 2021). "A similar study on mantle cell lymphoma suggested that patients with cyclin D1 overexpression had worse prognosis." (PMID 32697404, 2020).
mantle cell lymphoma (continued). "Strongly proliferative mantle cell lymphoma (MCL) tumors have exceptionally high Cyclin D1 mRNA levels, expressing short Cyclin D1 mRNA isoforms with truncated 3′ UTRs." (PMID 33419342, 2020). "In several types of cancer, including mantle cell lymphoma, a translocation often leads to over-expression of Cyclin D1 (CCND1)." (PMID 32560344, 2020). "On the contrary, FISH analyses should be performed in any case of:B cell lymphomas with blastoid morphology, with the exclusion of TdT+ lymphoblastic lymphoma or cyclin D1+ pleomorphic/blastoid mantle cell lymphoma." (PMID 31388760, 2019). "For example, an extremely rare type of MCL, “in situ” mantle cell lymphoma, is masked by HV-CD-like morphological characteristics, but cyclin D1-positive cells are expressed in the mantle zones of some lymphoid follicles." (PMID 31439011, 2019). "Mantle cell lymphoma (MCL) is a type of non-Hodgkin B cell lymphoma with a distinctive molecular marker cyclin D1 that is constitutively overexpressed in almost all cases." (PMID 30791947, 2019). "We then used these lipidoid nanoparticles to examine the effect of silencing a trio of genes—Cyclin D1, Bcl‐2, and Mcl‐1—on mantle cell lymphoma apoptosis and proliferation rates." (PMID 30065968, 2018). "Further promising results have been obtained in a vaccine against cyclin-D1 that is overexpressed by mantle cell lymphoma (MCL)." (PMID 29997628, 2018). "Overexpression and constitutive activation of CYCLIN D1 and Casein Kinase 2 are common features of many hematologic malignancies, including mantle cell lymphoma (MCL) and leukemias such as T-cell acute lymphoblastic leukemia (T-ALL)." (PMID 30701029, 2018). "Although several groups have used nanotherapeutics to knockdown Cyclin D1 with siRNA or shRNA in mantle cell lymphoma, other genes have been largely overlooked." (PMID 30065968, 2018). "Because of the availability of ancillary tests such as cyclin D1 in mantle cell lymphoma, it can be considered an “easy” diagnosis." (PMID 27956371, 2017). "Overexpression of E2F1 has been detected in mantle cell lymphoma and multiple myeloma, which closely related to the up-regulation of Cyclin D1." (PMID 29108247, 2017). "The shortening of the 3'UTR of cyclin D1 in mantle cell lymphoma offers provocative insights into this process." (PMID 28503306, 2017). "The sequence of the polyadenylation signal in mantle cell lymphoma appears to be critical for 3'end formation of the cyclin D1 transcript." (PMID 28503306, 2017). "In mantle cell lymphoma, for example, mutations that generate novel, gene-proximal PAS in the CCND1 3′ UTR have been discovered." (PMID 27205883, 2016). "Mantle cell lymphoma (MCL) is an aggressive B-cell-type non-Hodgkin lymphoma characterized by cyclin D1 overexpression and occurs more commonly in advanced ages and in males." (PMID 26377148, 2016). "For example, cyclin D1 (CCND1) translocation can be detected by FISH as a characteristic abnormality in mantle cell lymphoma, which provides differential diagnosis for morphologically similar chronic lymphoid leukemia (CLL)." (PMID 27656642, 2016). "Mantle cell lymphoma is an aggressive B-cell lymphoma characterized by IGH/CCND1 translocation resulting in overexpression of cyclin D1." (PMID 27600067, 2015). "In mantle cell lymphoma (MCL), deregulation of the CCND1 locus is prognostic and has been implicated as a driver of disease onset, but is dispensable for disease progression." (PMID 25787974, 2015). "The presence of CCND1 gene rearrangements or cyclin D1 abnormalities should be assessed in such cases to establish the diagnosis of mantle cell lymphoma and exclude other CD5−/CD10− mature B-cell neoplasms." (PMID 26347832, 2015).
mantle cell lymphoma (continued). "This study demonstrated that cyclin D1 represents a good target for immunotherapy and targeting cyclin D1 to DCs provides a new strategy for mantle cell lymphoma vaccine." (PMID 25888530, 2015). "For example, vorinostat suppresses cyclin D1 in mantle cell lymphoma cells by blocking the translation of cyclin D1 via inhibiting the phosphatidylinositol 3-kinase (PI3K)/Akt/mTOR/eIF4E-BP pathway most likely by PI3K inhibition." (PMID 26681199, 2015). "In a subset of mantle cell lymphoma, for example, a truncated Cyclin D1 transcript is over-represented, leading to an increase in Cyclin D1 protein expression." (PMID 24497914, 2014). "The immunohistochemical studies performed on the eyelid mass confirmed a monoclonal proliferation of B cells expressing cyclin-D1; therefore, a final diagnosis of mantle cell lymphoma was rendered." (PMID 23691402, 2013). "Recent evidence shows that miR-16-1 represses cyclin D1 expression at the post-transcriptional level via binding its 3′-UTR in mantle cell lymphoma." (PMID 23383271, 2013). "Few scattered cyclin D1+ nuclei were noted in some of these lymphoid aggregates, raising the suspicion of mantle cell lymphoma." (PMID 22953080, 2012). "For example in 7 out of 15 cases of mantle cell lymphoma expressing a truncated CCND1 mRNA a genomic deletion in the 3′ UTR region was detected, and in 3 other cases a point mutation led to the creation of premature polyadenylation sites." (PMID 22347440, 2012). "The monomorphic Cyclin D1 high proliferation observed in this case led to a diagnosis with other lymphomas, in particular with mantle cell lymphoma." (PMID 22770229, 2012). "Mantle cell lymphoma is characterized by a genetic translocation results in aberrant overexpression of the CCND1 gene, which encodes cyclin D1." (PMID 22905260, 2012). "Mantle cell lymphomas have been reported to over-express Cyclin D1 due to a characteristic genetic translocation." (PMID 21347341, 2011). "Referring to B- cell non Hodgkin lymphomas, cyclin D1 was mainly overexpressed in mantle cell lymphomas and large B- cell lymphomas whereas the other subtypes showed normal cyclin D1 expression." (PMID 21176227, 2010). "The histology and immuno-histochemistry of the excised small and large bowel revealed mantle cell lymphoma with multiple lymphomatous polyposis and positivity to Cyclin D1 marker." (PMID 19646237, 2009). "Tumors, e.g. mantle cell lymphomas, in which cyclin D1 is involved as an oncogene, overexpression or aberrant expression has been supposed to correlate with poor prognosis." (PMID 18651966, 2008). "Absence of CD10 and bcl-6 staining are useful for excluding follicular lymphoma, and staining of cyclin D1 is helpful for excluding mantle cell lymphoma." (PMID 17284308, 2007). "Cyclin D1 mRNA isoforms a and b were expressed in mantle cell lymphoma (MCL) and multiple myeloma (MM)." (PMID 17022831, 2006). "Cyclin D1 is also expressed in lymphoid tumors such as mantle cell lymphoma (MCL) and multiple myeloma (MM)." (PMID 17022831, 2006). "Overexpression of the cyclin D1 protein, a regulator of the early phases of the cell cycle through inactivation of the tumor suppressor retinoblastoma protein (pRb), plays an important role in the pathogenesis of mantle cell lymphoma (MCL)." (PMID 36006308, 2022). "These Hodgkin cells may also express markers of the associated lymphoma such as BCL2/BCL6 for follicular lymphoma and Cyclin D1 for mantle cell lymphoma, which may be combined with BCL2/BCL6 and CCND1 rearrangements in both contingents, respectively." (PMID 36428786, 2022). "However, CD20 and cyclin D1 are seldom positive in MM in contrast to other lymphoproliferative neoplasia where cyclin D1 is positive, such as mantle cell lymphoma (MCL) and hairy cell leukemia." (PMID 35846062, 2022).
mantle cell lymphoma (continued). "In comparison with other B-cell lymphomas, mantle cell lymphoma has a poorer prognosis, and positive immunochemical staining of cyclin D1 and SOX-11 is useful for differentiating mantle cell lymphoma from other appendiceal lymphomas and treating patients appropriately." (PMID 34442137, 2021). "Alterations of cyclin D1 resulting in nuclear protein expression is thought to promote tumorigenesis in various types of cancers, often as a result of CCND1 gene amplification, such as in breast, lung, bladder carcinomas, or as a result of CCND1 translocation in mantle cell lymphoma." (PMID 29969496, 2018). "In line with a destabilized G1/S border as a common denominator for CHK1 inhibitor sensitivity, other groups have reported that MYC-driven diffuse large B cell lymphoma and CCND1-driven mantle cell lymphoma display a marked sensitivity against the CHK1 inhibitor PF-47773650,51." (PMID 29138515, 2017). "Overexpression of cyclin D1 is a key feature of mantle cell lymphoma (MCL)." (PMID 25594062, 2014). "Repression of cyclin D1 from HDAC inhibitors was reported in mantle cell lymphoma." (PMID 23758695, 2013). "Cyclin D1 overexpression is the hallmark of mantle cell lymphoma, whereas cyclins D2 and D3 are reportedly not as specific to certain lymphomas as cyclin D1." (PMID 23675804, 2013). "In this study, we used RNA interference strategies to examine whether cyclin D1 might serve as a therapeutic target for mantle cell lymphoma." (PMID 22905260, 2012). "Immunohistochemically, malignant MALT lymphoma cells express markers of B-cell lineage, but are distinct from follicular lymphomas (which express CD10), mantle cell lymphomas (which express cyclin D1 and CD5), and small lymphocytic lymphomas (which express CD5 and CD23)." (PMID 21892966, 2011). "Mantle cell lymphomas express variable levels of cyclin D1 at both transcript and protein levels." (PMID 21176227, 2010). "Overexpression of cyclin D1 may occur through multiple mechanisms, including chromosomal translocation events (e.g. Mantle cell lymphomas), gene amplification (common in breast and oesophageal cancers), and defects in protein processing or transport." (PMID 17375037, 2007). "Using mantle cell lymphoma (MCL) as a naturally occurring model of cyclin D1 overexpression, we examined the impact of cyclin D1 on RS and DSB repair mechanisms." (PMID 40608419, 2025). "The emergence of IGH::CCND1 presents a diagnostic dilemma, raising questions about whether this rearrangement is a secondary event within the CLL clone or an independent process diagnostic for mantle cell lymphoma." (PMID 39691246, 2024). "It has been found that Deferasirox (DFX) can trigger the proteolysis of cyclin D1 in mantle cell lymphoma (MCL), which requires the participation of GSK-3β." (PMID 36829936, 2023). "On one hand, CCND1-dependent transcriptional program has been found to play an important role in the oncogenesis and tumor development and even could predict clinical outcome of some types of cancer such as mantle cell lymphoma." (PMID 35365622, 2022). "Moreover, Hodgkin cells may express specific markers of the associated lymphoma (e.g., BCL2/BCL6 for follicular lymphoma and Cyclin D1 for mantle cell lymphoma), sometimes combined with common BCL2/BCL6 or CCND1 rearrangements, respectively." (PMID 36428786, 2022). "Mantle cell lymphoma (MCL) is a rare subtype of non-Hodgkin’s lymphoma (NHL) manifesting rearrangement of cyclin D1." (PMID 35296646, 2022). "Mantle cell lymphoma (MCL) accounts for 5-6% of non-Hodgkin lymphomas, with characteristic expression of cyclin D1 due to CCND1-IGH gene rearrangement." (PMID 34527580, 2021).